CYP1A1 (cytochrome P450 family 1 subfamily A member 1)
Diseases named in the same sentence as CYP1A1 in open-access papers (continued):
Sharing a sentence is not in itself a finding about the gene and the disease.
injury (2 papers, 2023 to 2024). Damage inflicted on the body as the direct or indirect result of an external force, with or without disruption of structural continuity. "It was found that the inhibition of CYP1A1 could effectively improve liver injury, oxidative stress and pyroptosis induced by colchicine, while the activation of CYP1A1 aggravated colchicine-induced liver injury." (PMID 38251251, 2024).
ischemia (2 papers, 2019 to 2021). A hypoperfusion of the BLOOD through an organ or tissue caused by a PATHOLOGIC CONSTRICTION or obstruction of its BLOOD VESSELS, or an absence of BLOOD CIRCULATION. "When CYP1A1 expression was measured during ischemia, CYP1A1 mRNA levels increased in both the cerebral cortex and striatum at 3 and 6 h." (PMID 33804845, 2021). "DIM (1, 10 μM) partially normalized ischemia-induced changes i.e., it reduced the AhR, CYP1A1, Fas, and BECN1 immunolabeling." (PMID 30778709, 2019).
leukopenia (2 papers, 2018 to 2021). "A G allele variant of CYP1A1 (2455A>G) in patients with RCC has been associated with an increased risk of leukopenia." (PMID 29788981, 2018).
liver cirrhosis (2 papers, 2013 to 2024). "Results revealed that the m2/m2 CYP1A1 genotype makes individuals more susceptible to developing liver cirrhosis." (PMID 39062040, 2024). "At variance with CYP1A1, a significant level of CYP1A2 mRNA was present in uninduced healthy rats (about 500 times higher than that of CYP1A1), which decreased markedly with increasing severity of liver cirrhosis." (PMID 23626760, 2013). "However, carriers of the CYP1A1 variants m1 and m3 were not more prone to developing liver cirrhosis or HCC." (PMID 39062040, 2024).
liver diseases (2 papers, 2015 to 2024). "Evidence suggests that decreased expression of GSTP1 or CYP1A1 induced by polymorphisms at their respective gene loci has been associated with many liver diseases such as hepatocellular carcinoma." (PMID 25798582, 2015). "In addition, decreased GSTP1 and CYP1A1 expression induced by methylation of the GSTP1 and CYP1A1 promoters, respectively, has been reported in many liver diseases such as acute-on-chronic hepatitis B liver failure." (PMID 25798582, 2015).
lung disease (2 papers, 2020 to 2022). "KEGG analysis suggested that metabolism of xenobiotics by cytochrome P450 (CYP1B1, CYP1A1 and ALDH3A1), an important signalling pathway that influences the xenobiotic metabolizing capability of the lung and the risk of developing of lung diseases, was associated with COPD." (PMID 32961012, 2020). "CYP1A1 metabolizes multiple exogenous and endogenous substrates, which is mainly controlled by the aryl hydrocarbon receptor (AHR) and has been found to be involved in lung disease including COPD by regulating inflammation and oxidative stress." (PMID 36578523, 2022).
lymphoma (2 papers, 2004 to 2023). A malignant (clonal) proliferation of B- lymphocytes or T- lymphocytes which involves the lymph nodes, bone marrow and/or extranodal sites. "Important roles of Cyp1b1 in PAH carcinogenesis have been proposed by Gonzalez and co-workers who observed that Cyp1b1 knock-out mice expressing significant levels of Cyp1a1 are highly resistant to lymphoma formation by 7,12-DMBA." (PMID 15315710, 2004). "In addition, the expression of AhR, CYP1A1, CYP1B1, RUNX1 and SLC7A8 was upregulated in MEPs of individuals with lymphoma, concomitant with enhanced nuclear localization of AhR." (PMID 37919525, 2023).
mastitis (2 papers, 2018 to 2019). Inflammation of breast tissue during lactation or postpartum due to an obstructed duct or infection. "To further validate the CYP1A1 expression from the result of high-throughput sequencing, we extracted total mRNA from bovine normal mammary tissue and mastitic mammary tissue with clinical mastitis caused by E. coli and then analyzed CYP1A1 gene expression by RT-qPCR." (PMID 29686530, 2018). "This corroborates previous findings that inflammatory conditions, induced by LPS or found during mastitis, suppress CYP1A1 expression in mammary epithelial cells." (PMID 30615637, 2019). "To verify the functions of CYP1A1 in the bovine epithelial cells during bovine mastitis, we successfully cloned the full-length bovine CYP1A1 cDNAs as indicated by the PCR result, which showed a specific band at the right base pair size of 1573 bp." (PMID 29686530, 2018). "In subsequent experiments, we used LPS to treat the immortalized mammary epithelial cell line of MAC-T to investigate the functions of CYP1A1 in epithelial cells during bovine mastitis." (PMID 29686530, 2018). "Results showed that CYP1A1 gene expression was significantly lower in the tissue with mastitis than in the normal tissue." (PMID 29686530, 2018). "Results of this study showed that CYP1A1 expression was significantly downregulated in the mammary tissue of bovine with mastitis, in inflammatory epithelial cells (INEs) extracted from the tissue, and in lipopolysaccharide- (LPS-) induced INEs compared with their corresponding counterparts." (PMID 29686530, 2018). "In summary, the results of this study suggest that CYP1A1 plays important roles in mammary epithelial cells during bovine mastitis caused by the Gram-negative bacterial cell wall component LPS." (PMID 29686530, 2018).
multiple myeloma (2 papers, 2018 to 2021). "When notch ligand Dll1 on BM stromal cells binds to Notch2 receptor on myeloma cells, a cascade results that upregulates a cytochrome P450 enzyme involved in drug metabolism (CYP1A1), which ultimately leads to PI resistance." (PMID 29765356, 2018). "Treatment of cells with α-Naphthoflavone or CYP1A1 siRNA reintroduced PI sensitivity in myeloma cells." (PMID 29765356, 2018).
nicotine dependence (2 papers, 2014 to 2019). Physical and psychological dependence on nicotine. "One SNP (rs4646421) in CYP1A1 was significantly associated with nicotine dependence (p = 0.017, FDR q = 0.043) but its indirect effect on lung ADC became insignificant after multiple comparison justification." (PMID 25233467, 2014).
oral squamous cell carcinoma (2 papers, 2023). "The CYP1A1 gene encodes an aromatic hydrocarbon hydroxylase that induces the biotransformation of aromatic tobacco carcinogens and may play a key role in the pathogenesis of oral squamous cell carcinoma (OSCC) through the MspI polymorphism." (PMID 37391706, 2023). "Overexpression of common genes associated with tobacco-induced oral squamous cell carcinoma (OSCC), such as MMP1, MMP3, MMP9, YAP1, CYP1A1, and CYP1B1, was also observed." (PMID 36835505, 2023).
pancreatic cancer (2 papers, 2000 to 2014). "While SNPs in the phase I and II metabolism genes CYP1A1, GSTM1, GSTT1 and GSTP1 alone did not correlate with pancreatic cancer risk, a significant interaction between smoking and the GSTT1 null genotype was reported in Caucasian pancreatic cancer subjects." (PMID 24651674, 2014).
papillary thyroid cancer (2 papers, 2008 to 2020). "A study has demonstrated an inverse association between germline CYP1A1 inheritance and smoking with risk of papillary thyroid cancer." (PMID 33316920, 2020).
prostate tumor (2 papers, 2018 to 2021). "For example, for the gene “CYP1A1”, the associated disease in the gold standard is “Prostatic Neoplasms” which is supported by 38 publications in GAD and 2 publications in CTD_curated." (PMID 30591010, 2018). "The other major extrahepatic P450 isoform expressed in normal and prostate tumor is CYP1A1, bergamottin is a competitive inhibitor of CYP1A1 and can aid in cancer chemoprevension due to CYP1A1s role in carcinogenesis, this inhbitory effect is independent of bergamottins affect on CYP3A5 and AR." (PMID 34570813, 2021).
pulmonary embolism (2 papers, 2018 to 2023). The obstruction of the pulmonary artery or one of its branches by an embolus, sometimes associated with infarction of the lung. "In summary, either one of the two functional variants of CYP1A1 was found in all patients with pulmonary embolism." (PMID 29368655, 2018). "A particularly interesting finding was that at least one of the functional variants of CYP1A1 was identified in pulmonary embolism cases in this study." (PMID 29368655, 2018). "Rs1048943 on CYP1A1 was found in nine patients including two patients with pulmonary embolism (SN1932 and SN9899), and the carrier frequency in cases was significantly higher than in controls using Fisher’s exact test (P = 0.046)." (PMID 29368655, 2018). "Rs4646422 on CYP1A1 was found in four patients including one patient with pulmonary embolism (SN8592)." (PMID 29368655, 2018).
rectal cancer (2 papers, 2010 to 2017). A primary or metastatic malignant neoplasm that affects the rectum. "Carriers of the CYP1A1 rs4646903 CC homozygous variant showed a reduced risk of rectal cancer compared with that in TT carriers." (PMID 28273931, 2017). "However, when the data were stratified by the anatomic site, homozygous variant of CYP1A1 rs4646903 showed an inverse association with the risk of rectal cancer (OR [95% CI] = 0.64 [0.42, 0.98], CC vs. TT)." (PMID 28273931, 2017).
systemic lupus erythematosus (2 papers, 2021 to 2023). An autoimmune multi-organ disease typically associated with vasculopathy and autoantibody production. "The abnormal expression of CYP1A1 might be related to the progression of systemic lupus erythematosus." (PMID 38137330, 2023).
xeroderma pigmentosum (2 papers, 2021 to 2025). Xeroderma pigmentosum (XP) is a rare genodermatosis characterized by extreme sensitivity to ultraviolet (UV)-induced changes in the skin and eyes, and multiple skin cancers. "Moreover, polymorphism in several DNA repair genes, such as X-ray repair cross-complementing protein 1 (XRCC1), xeroderma pigmentosum group D 6 (XPD6) and 23 (XPD23), and cytochrome P450 1A1 (CYP1A1), was observed to be associated with high or medium DNA damage after exposure to air pollution." (PMID 40141439, 2025).
adrenal cortical carcinoma (1 paper, 2023). "To investigate whether CYP1B1 may also be a minor pregnenolone synthesis pathway in peripheral steroidogenic cells, we examined the effects of CYP1A1/CYP1B1 inhibitors and siRNA knockdown on human adrenal cortical carcinoma cells H295R-S1." (PMID 37442234, 2023).
age-related macular degeneration (1 paper, 2022). Age-related loss of vision in the central portion of the retina (macula), secondary to retinal degeneration. "Up-regulates AhR target genes CYP1A1 and CYP1B1 and may prevent age-related macular degeneration." (PMID 35566359, 2022).
AIDS (1 paper, 2018). A syndrome resulting from the acquired deficiency of cellular immunity caused by the human immunodeficiency virus (HIV). "HIV/AIDS disease progression was assessed by measuring CD4+ cell count and viral load of the patients, and GST polymorphism was determined by amplifying the GSTT1 and GSTM1 genes using multiplex PCR, with CYP1A1 gene as an internal control." (PMID 29795558, 2018).
alcoholic liver cirrhosis (1 paper, 2021). A disorder of the liver characterized by the presence of fibrotic scar tissue instead of healthy liver tissue. "The results showed that subjects with an m2/m2 CYP1A1 genotype were more likely to have alcoholic liver cirrhosis." (PMID 34869335, 2021).
amoebiasis (1 paper, 2016). "CYP1A1 and SERPINB2 displayed high expression levels along with T. gondii infection, and these two genes are involved in chemical carcinogenesis and amoebiasis, respectively." (PMID 27242740, 2016).
Ascites (1 paper, 2013). Accumulation of fluid in the peritoneal cavity (between the layers of the peritoneum that lines the abdomen). "Normalization of signal intensity to the amount of protein loaded per lane showed that CYP1A1 and CYP1A2 were induced to similar levels in healthy and non-ascitic cirrhotic rats, whereas their induction was significantly lower in rats with ascites." (PMID 23626760, 2013).
astrocytomas (1 paper, 2015). "In astrocytomas, when examining whether WHO-tumor-grade correlates with gene- or protein-expression levels, we found that higher tumor grades were associated with a decreased protein expression for AOX1 and CYP1A1 (data not shown)." (PMID 26580399, 2015).
Azoospermia (1 paper, 2017). Absence of any measurable level of sperm,whereby spermatozoa cannot be observed even after centrifugation of the semen pellet. "Thestudy was therefore designed to investigate the associationof the CYP1A1*2A polymorphism withidiopathic non-obstructive azoospermia and to assessthe impact of the status of life style factorson the relationship between the polymorphism andsusceptibility to idiopathic non-obstructive azoospermia." (PMID 28868835, 2017).
bacterial sepsis (1 paper, 2022). "The loss of CYP1A1, which protects against bacterial sepsis, limits the abundance of E. faecalis and increases taxa associated with metabolic health, such as Intestinimonas butyriciproducens, under MRSA challenge." (PMID 35572636, 2022).
Bovine mastitis (1 paper, 2018). INFLAMMATION of the UDDER in cows. "Hence, CYP1A1 may be a useful therapeutic target mitigating the injury caused by inflammatory overreaction, thus easing the worry of increasingly growing cost every year on bovine mastitis." (PMID 29686530, 2018). "The functions and potential mechanism of CYP1A1 in proliferation and the inflammatory cytokine secretion in epithelial cells induced by LPS were further clarified using an in vitro epithelial cell model of bovine mastitis." (PMID 29686530, 2018).
cholestasis (1 paper, 2023). Impairment of the bile flow caused by obstruction within the liver, or outside the liver in the bile duct system. "Prior studies indicate that Cyp1a1, Cyp1a2, and Cyp2b1 are potential targets for treating of cholestasis." (PMID 37881184, 2023). "The genes regulated in all pathways, Cyp1a1, Cyp1a2, Cyp2a1, Cyp2b1, Cyp4a8, Cyp2c11, Rdh16, Alox15, Ephx2, Sult2a1, and Acox2, were the potential targets for ZYP treatment of cholestasis." (PMID 37881184, 2023).
chorioamnionitis (1 paper, 2012). A morphologic finding indicating inflammation of the fetal sac membranes. "They found a very strong interaction between maternal active smoking and the joint genotypes (CYP1A1“AG/GG”+GSTT1 “null”) in the risk of PTD accompanied by histologic chorioamnionitis." (PMID 23152866, 2012).
choroidal neovascularization (1 paper, 2025). An eye disorder described by the growth of new blood vessels that originate from the choroid through a break in the Bruch membrane into the sub–retinal pigment epithelium (sub-RPE) or subretinal space. "Moreover, CYP1A1 has been implicated in ocular neovascular diseases such as choroidal neovascularization." (PMID 41209569, 2025).
cleft palate (1 paper, 2022). Cleft palate is a fissure type embryopathy that affects the soft and hard palate to varying degrees. "This suggests that factors other than CYP1A1 may also be associated with the development of cleft palate induced by TCDD." (PMID 35745180, 2022). "To determine whether reduced expression of CYP1A1 is associated with a reduced incidence of cleft palate in vivo, we performed the EdU assay and immunohistochemical staining for cell proliferation and CYP1A1 accumulation in the palate of mouse fetuses." (PMID 35745180, 2022). "In conclusion, quercetin reduces the development of TCDD-induced cleft palate in mice by inhibiting CYP1A1 via AhR." (PMID 35745180, 2022). "In conclusion, our results suggest that quercetin reduces the development of TCDD-induced cleft palate by inhibiting CYP1A1 through AhR." (PMID 35745180, 2022). "Further elucidation is needed to determine whether activation of genes other than CYP1A1 is involved in cleft palate, or whether it is due to an unknown pathway other than transcriptional activation mediated by AhR." (PMID 35745180, 2022). "However, the activation of genes related to drug metabolism, such as CYP1A1, alone cannot fully explain the development of malformations such as cleft palate." (PMID 35745180, 2022). "However, despite the fact that CYP1A1 protein expression is largely suppressed in vitro, it does not completely prevent TCDD-induced cleft palate in vivo." (PMID 35745180, 2022).
conduct disorder (1 paper, 2018). A disorder diagnosed in childhood or adolescence age group characterized by aggressive behavior, deceitfulness, destruction of property or violation of rules that is persistent and repetitive, and within a one year period. "Despite the small size of the population studied, DNA methylation at AHRR and GFI1, but not at CYP1A1, were shown to be related to the severity of conduct disorder and ADHD in children of smoking mothers." (PMID 29618728, 2018).
craniosynostosis (1 paper, 2020). Craniosynostosis is defined as the premature fusion of one or more cranial sutures leading to secondary distortion of skull shape resulting in skull deformities with a variable presentation. "In the second patient (HB46), a syndromic male with craniosynostosis and dysmorphic signs, another CYP1A1 variant mapping in the same exon that the one observed in the previous patient was detected." (PMID 32432034, 2020).
dilated cardiomyopathy (1 paper, 2024). Cardiomyopathy which is characterized by dilation and contractile dysfunction of the left and right ventricles. "The presence of CYP1A1 mRNA has also been observed in the right ventricle and left atrium among patients with dilated cardiomyopathy." (PMID 39188949, 2024).
folliculitis (1 paper, 2022). Inflammation of the hair follicles. "Besides concerns on phase 1 metabolism by CYP1A1 due to AHR activation, a specific side effect, folliculitis, is reported in patients treated with topical AHR-activating therapies, such as coal tar and tapinarof." (PMID 35163694, 2022).
gallbladder cancer (1 paper, 2019). "Tsuchiya (2007) reported a positive association between genetic polymorphism of CYP1A1, which metabolizes chemical pollutants discharged into the environment, and gallbladder cancer risk in Japanese and Hungarians." (PMID 31870105, 2019). "In this study, we speculated that agricultural chemical pollution in the environment may be a critical risk factor for gallbladder cancer and examined if genetic variants of CYP1A1, GSTM1, or GSTT1 were associated with gallbladder cancer risk." (PMID 31870105, 2019). "Some studies have examined the associations between CYP1A1, GSTM1, and GSTT1 polymorphisms and gallbladder cancer risk, but the findings have been inconsistent." (PMID 31870105, 2019).
Hepatitis (1 paper, 2018). Inflammation of the liver. "Among all the differentially expressed genes in the LPS-treated cells relative to the untreated cells, CYP1A1 has attracted our attention because of its important role in inflammation-associated diseases, such as hepatitis." (PMID 29686530, 2018). "The differential expression of CYP family members, including CYP1A1, is significant in LPS-induced hepatitis." (PMID 29686530, 2018).
interstitial lung disease (1 paper, 2011). A diverse group of lung diseases that affect the lung parenchyma. "Hydroxyaniline metabolites produced by CYP1A1 can be oxidized to reactive quinone-imine derivatives that form adducts with nucleophilic groups of macromolecules or GSH and may be related to clinically relevant hepatotoxicity or interstitial lung disease." (PMID 22111840, 2011).
learning disabilities (1 paper, 2025). "Reported genetic variants associated with tobacco smoke metabolite processing (maternal CYP1A1, GSTT1, GSTM1, and norepinephrine transporter gene SLC6A2913) may influence polymorphisms in norepinephrine and dopamine transporter genes in offspring, increasing the risk of learning disabilities." (PMID 41445786, 2025).